BDNF (brain derived neurotrophic factor)
Diseases named in the same sentence as BDNF in open-access papers (continued):
Sharing a sentence is not in itself a finding about the gene and the disease.
Anxiety (continued). "In rodent studies, social isolation resulted in decreased hippocampal ALLO and BDNF levels, whereas ALLO administration prevented anxiety-depressive behaviors, impaired neurogenesis, and reduced BDNF expression." (PMID 41155366, 2025). "Maternal trait anxiety was assessed using the Stait-Trait Anxiety Inventory (STAI-Y) and infants' BDNF DNAm at birth was assessed in 11 CpG sites in buccal cells." (PMID 41390788, 2025). "Behavioral assessments were used to evaluate anxiety- and depressive-like symptoms, and biochemical analyses measured oxidative stress markers, serotonin levels, MAO activity, BDNF, and GFAP as indicators of neuroinflammation in the prefrontal cortex." (PMID 40780966, 2025). "To explore the specific role of astrocytic BDNF in anxiety modulation, we used AAV-mediated short hairpin RNA (shRNA) to knock down BDNF expression in hippocampal astrocytes." (PMID 40777598, 2025). "The brain-derived neurotrophic factor (BDNF), catecholamine-O-methyltransferase (COMT), and FK506-binding protein 5 (FKBP5)-gene are other possible genetic markers for altered anxiety levels." (PMID 40094863, 2025). "Gut microbiota transplantation induces anxiety behavior in IBS model mice, accompanied by reduced BDNF expression and impaired neuroplasticity." (PMID 40696692, 2025). "Consistent with previous studies, CUMS markedly downregulated BDNF, TrkB, and CREB expression in the hippocampus, leading to synaptic dysfunction and anxiety-like behavior." (PMID 41516248, 2025). "The increase in these variables is correlated with decreased BDNF expression in the cortex and reduced entries into the open arms of the EPMT (anxiety)." (PMID 41237192, 2025). "BDNF also displayed significant correlations with both total HADS (p = 0.028) and anxiety section scores (p = 0.014)." (PMID 40491453, 2025). "This decreases brain-derived neurotrophic factor (BDNF) and nerve growth factor (NGF) production within the hippocampus and promotes the development of anxiety." (PMID 39851502, 2025). "Some research suggests that supplementing with these minerals can have mild antidepressant and anxiety-reducing effects, likely by helping to normalize the activity of the HPA axis and boosting the expression of brain-derived neurotrophic factor (BDNF)." (PMID 41374018, 2025). "Our data showed that astrocytic BDNF knockdown resulted in up-regulation of IFN signaling, possibly exacerbating anxiety sensitivity through altered astrocytic activity and a disrupted neuroimmune environment." (PMID 40777598, 2025). "Notably, HSP resulted in a significant attenuation of anxiety- and depression-associated behaviors, a reduction in pro-inflammatory cytokine levels (TNF-α, IFN-γ, IL-1β, IL-2, IL-6), and an augmentation of neurotrophic factors (NT-3, BDNF, NGF) within the striatum." (PMID 41346684, 2025). "Chronic administration of NP to male rats resulted in downregulation of the brain-derived neurotrophic factor (BDNF)-TrkB-CREB signaling network in the hippocampus, contributing to anxiety-like behavior." (PMID 39280932, 2024). "Lactobacillus helveticus NS8 shows anti-inflammatory effects, reduces post-restriction anxiety, improves memory, and decreases corticosterone and ACTH levels, with an increase in BDNF mRNA in the hippocampus." (PMID 38673018, 2024). "Exercise partially reversed the anxiety-like behaviours and pattern separation impairment induced by antibiotics by maintaining AHN and BDNF levels and reducing the activation state of the microglia and peripheral inflammatory status." (PMID 38658547, 2024). "This study found that tobacco smoke exposure for 36 days induced anxiety-like behavior as measured through OF, LDB, and EPM, as well as induced neuroinflammation through upregulation of NF-κB and downregulation of BDNF in HIP and HYP brain regions." (PMID 39195700, 2024).
Anxiety (continued). "In the present study, we provided reliable demonstrations that BRL-50481 ameliorated stress induced anxiety-like behaviors and severe conditioned fear responses in SPS mice by increasing the level of cAMP and activating the BDNF/TrkB pathway in hippocampus." (PMID 39092219, 2024). "BDNF and Drebrin expression in the PFC has been suggested to correlate with anxiety-like behaviors in rodents." (PMID 38769131, 2024). "Physical training can upregulate growth factors, like Brain-Derived Neurotrophic Factor (BDNF), stimulate neurogenesis and angiogenesis, facilitating functions of brain regions particularly related to anxiety or stress, aiding in reducing anxiety symptoms." (PMID 38500549, 2024). "The primary outcome variable was the correlation between anxiety scores (APAIS, MDAS, STAI, VAS) and serum BDNF level." (PMID 38907644, 2024). "Genetic models of T2D, such as the db/db mice, also showed anxiety-like behavior, increased levels of inflammatory cytokines (IL-1β, TNF-α, and IL-6), and reduced levels of BDNF in the hippocampus." (PMID 38279738, 2024). "In addition, the observation of 324 people found that the low serum content of BDNF was significantly correlated with the anxiety disorder reflected by the temperament characteristics survey (p = .009), so that the reduction of serum BDNF content may be a biochemical sign of anxiety." (PMID 37118929, 2023). "As alterations in neurotransmitter and BDNF expression have been observed in response to anxiety, we aimed to explore the interplay among behavior, serum corticosterone, ACTH, neurotransmitters, and BDNF expression in mice." (PMID 37867495, 2023). "Together, our results suggest that excessive alcohol drinking in the Met68BDNF may be attributed, in part, to heighted social anxiety and a lack of alcohol-dependent anxiolysis, a phenotype that is associated with malfunction of BDNF signaling in the vHC of male Met68BDNF mice." (PMID 36622381, 2023). "However, the linkage of bidirectional changes in the BDNF level in the SH-SY5Y cells to the regulation of anxiety- and pain-like responses remains unclear because either increases or decreases in the level of BDNF associated with psychological stress could be dependent on the areas in the brain." (PMID 37764773, 2023). "Salivary gland-derived brain-derived neurotrophic factor increases hippocampal GABA and attenuates anxiety behavior via the brain-salivary gland connection in mice." (PMID 37429932, 2023). "In this study, we found that plasma corticosterone level and BDNF gene expression in the PFC was significantly decreased in the gestationally arsenic-exposed F1 female mice, which is also correlated with anxiety-like behaviors in those mice." (PMID 37407491, 2023). "CAPS2 knockout mice exhibited impaired activity-dependent BDNF secretion, reduced late-phase long-term potentiation at CA3–CA1 synapses, decreased hippocampal theta oscillation frequency, and increased anxiety-like behavior." (PMID 37238659, 2023). "Moreover, even in a mouse model of post-traumatic stress disorder, in which the animals witnessed defeat events, the stress may provoke anxiety-like behaviours related to decreased BDNF levels in the hippocampus and medial prefrontal cortex and increased BDNF levels in the amygdala." (PMID 37108250, 2023). "Information was obtained from 19 patients using the State-Trait Anxiety Inventory (STAI) and analysis of BDNF, NSE and S100B serum levels." (PMID 38055476, 2023). "BDNF plays an important regulatory role in synaptic function and plasticity within specific circuitry of the HIP in the context of anxiety-like behaviors." (PMID 35722162, 2022). "In light of these considerations, in this study, we examined whether low- and high-anxiety PS rats were associated with different corticosterone concentrations, rates of brain blood flow, alterations in NAA and PEA levels, free radical oxidation levels, and BDNF concentrations in the hippocampus." (PMID 36012411, 2022).
Anxiety (continued). "Different molecular signaling pathways, such as BDNF, TrkB, TLR2, and TLR4, are involved in the pathogenesis of anxiety and cognitive decline." (PMID 35898162, 2022). "Given the well-established involvement of the BDNF/TrkB system in anxiety, we sought to rescue the reduced anxiety observed in the open field test by chronic administration of 7,8-DHF, a known agonist of BDNF signaling." (PMID 35140204, 2022). "This study postulated that minocycline reduces hyperphosphorylated tau protein levels, upregulates the BDNF/CREB signalling pathway in the mPFC, and ameliorates LPS-induced locomotor deficits and anxiety-like behaviour." (PMID 36362262, 2022). "Brain-derived neurotrophic factor (BDNF), as an important neurotrophic factor, is also involved in the aetiology and treatment of anxiety." (PMID 36545308, 2022). "All volunteers took the blood test for BDNF, mitochondrial oxidative phosphorylation (OXPHOS), Cortisol, and Heart rate variability (HRV) measurement before and Visual Analogue Scale for Anxiety (VAS-A), forward and backward digit span after each period." (PMID 35757176, 2022). "BDNF is one of the most important regulators of brain signaling and synaptic plasticity, and the BDNF‐TRKB signaling pathway plays an important role in cognitive function, memory, and anxiety." (PMID 34448534, 2021). "Germ-free mice with concurrent upregulation of stress response have shown a reduction in BDNF levels, alteration in NMDA levels, and have increased anxiety with the deterioration of neurological functions." (PMID 33946488, 2021). "The strain 001 group induced a higher increase in BDNF gene expression in zebrafish brain than strain 002 and BCRC 81387, which revealed that 001 tempeh had an effect similar to that of anti-anxiety chemicals and antidepressants." (PMID 34884465, 2021). "In this regard, some evidence indicated that animals characterized by low BDNF expression in several brain regions, including amygdala (AMY), display anxiety-like behaviors together with higher alcohol preference." (PMID 33671048, 2021). "BDNF is also involved in the pathogenesis of neuropsychiatric disorders, such as schizophrenia, major depressive disorder (MDD), bipolar disorder, anxiety, and eating disorders." (PMID 34640441, 2021). "Inochinohaha White is considered a medicine primarily used to treat PMS by attenuating anxiety-like behavior through GABAA receptor and brain-derived neurotrophic factor expression, which composed of 11 herbs: Angelica sinensis (Oliv)." (PMID 35185533, 2021). "Thus, it is likely that BDNF may affect ACC related anxiety." (PMID 34526080, 2021). "A study of chronic colitis that induced an anxiety-like behavior in rats showed increased TNF-a levels and concurrent suppressed expression of brain-derived neurotrophic factor." (PMID 33498197, 2021). "In summary, this study demonstrated that PMS increased CORT secretion, down-regulated BDNF expression in the PFC, and induced anxiety-like behavior in adolescent pups." (PMID 32793001, 2020). "The significant elevation and reduction in the hippocampus of relative mRNA levels of brain-derived neurotrophic factor and interleukin 1β, respectively, also showed the neuroprotective role of GORZ in ethanol-induced anxiety." (PMID 32606350, 2020). "In conclusion, P-CA is a representative compound from AOM for its bioactivities of activating BDNF/TrkB/AKT signaling pathway, promoting hippocampal neurogenesis, improving cognitive functions, and reducing anxiety in post–ischemic stroke rats." (PMID 33537297, 2020). "HSE treatment completely prevented the anxiety-induced reduction of p-ERK44 and BDNF and the increase of CREB, and brought the levels back to the naïve group ones." (PMID 33348565, 2020).
Anxiety (continued). "In the present study, the treatment of P-CA up-regulated the expression of BDNF, TrkB receptor, and p-AKT; promoted hippocampal neurogenesis; enhanced spatial learning; increased short and long-term memory; and attenuated anxiety in ischemic stroke rats." (PMID 33537297, 2020). "Decreasing BDNF or ARC expression in the CeA of rodent models of alcoholism in adulthood increases drinking and anxiety-like behaviors, which are measures of alcohol dependence." (PMID 30728347, 2019). "Regular physical activity has been related to reduced anxiety due to its impact on some pathological mechanisms, such as modulation of HPA and an increase of brain-derived neurotrophic factor (BDNF) levels and β-endorphins." (PMID 31159322, 2019). "In identifying the brain region responsible for early weaning-induced anxiety, we considered the PFC a candidate because BDNF expression is correlated with fear-related memory in early-weaned mice." (PMID 30850750, 2019). "Since Ghsr-/- mice showed normal baseline level of BDNF, but higher concentration of BDNF after CSDS than Ghsr+/+ control mice, we proposed that such elevation may associate with GHS-R1a deficiency-induced behavioral resistance to CSDS, such as reduced anxiety and despair." (PMID 31057357, 2019). "This suggests that early weaning-induced corticosterone secretion inhibits PFC BDNF signaling and decreases PFC regulation of the basolateral amygdala, resulting in increased anxiety." (PMID 30850750, 2019). "These treatments also increased anxiety-like behaviors and suppressed hippocampal CREB phosphorylation and BDNF expression." (PMID 30224732, 2018). "In summary, two weeks of chronic stress induced anxiety and despair in mice, as measured by the OFT and FST and by levels of cortisol, serotonin, proinflammatory cytokines, and CREB/BDNF." (PMID 30065945, 2018). "Within the FM cohort, patients with the CG genotype of BDNF rs11030102 had more severe fatigue symptoms (measured by the BFI) and anxiety symptoms (measured by the STAI-I) than did the other genotypes (P = 0.001 and P = 0.032, respectively)." (PMID 30285822, 2018). "In the clinical measures, only anxiety, assessed using the STAI-II score, was significantly different among the patients according to BDNF haplotype." (PMID 30285822, 2018). "Therefore, it would seem important to examine the effects of BDNF/GR crosstalk by testing how mice with the BDNF Val66Met allele compare with mice lacking the BDNF-sensitive GR phosphorylation sites in various regions of the brain to protect or exacerbate anxiety- or diet-induced obesity or both." (PMID 28781762, 2017). "The link between BDNF-TrkB signaling and GAD1-GABA signaling plays an essential role in improvement of the anxiety state." (PMID 28872625, 2017). "The skeletal muscle production of brain-derived neurotrophic factor (BDNF), inflammation and oxidative stress play a role in the modulation of mood and anxiety." (PMID 27832209, 2016). "Chronic pretreatment with Xiaoyaosan or antalarmin significantly reversed elevated anxiety-like behavior and the upregulated level of CRF1R and BDNF in the amygdala of stressed rats." (PMID 27042185, 2016). "The observed reduction in the BDNF level in LTSC mice and their behavior reinforce the previous reports in rodents and PTSD patients demonstrating anxiety-like behavior with varied levels of BDNF." (PMID 26016844, 2015). "Restraint stress was known to decrease expression of hippocampal BDNF, activate the HPA axis, and result in increased anxiety-like behavior in rodents." (PMID 25179125, 2014). "Indeed, the increase in hippocampal expression of BDNF in response to voluntary wheel-running and 1-week forced treadmill exercise in rodents has been attributed to improvement in cognitive functions and reduction in anxiety- and depressive-like behaviors by some authors." (PMID 24772064, 2014).
Anxiety (continued). "In adult rats, high cholesterol diet induced anxiety-like behavior and increase of serum CORT and decrease of hippocampal BDNF comparing with their respective control group that fed the regular diet." (PMID 25179125, 2014). "We recently showed that expression of Sst, Gad67, and Gad65 is dependent upon brain-derived neurotrophic factor (BDNF) signaling, and reports also indicate sexually dimorphic effects of reduced BDNF signaling on anxiety-/depressive-like behaviors." (PMID 24062698, 2013). "Similarly, it may be interesting to explore the possibility that innate abnormalities in chromatin structure may affect BDNF levels, resulting in innate anxiety-like behaviors, such as those demonstrated by P rats, that may be critical to the development of alcoholism." (PMID 23584115, 2012). "BDNF, as well as type 2 corticotrophin releasing factor receptor (CRFR) 2, has been shown to mediate anxiety-like behavior." (PMID 21977046, 2011). "Intriguingly, chronic unpredictable stress dramatically increases mRNA expression of PACAP and brain-derived neurotrophic factor (BDNF) in the dorsal part of the BNST, a region of the central extended amygdala that mediates fear- and anxiety-like behavior." (PMID 21524255, 2011). "Besides neurogenesis, BDNF has been hypothesized to have a crucial effect on anxiety." (PMID 20862278, 2010). "Furthermore, we hypothesize that this seasonal decline will be moderated by intrinsic factors, expecting that individuals with lower cognitive function, higher anxiety, and poorer physical health will be more susceptible to the negative impact of winter on BDNF homeostasis." (PMID 41164095, 2025). "Our findings are supported by a previous study demonstrating that AGOM treatment decreased the release of cytokines (TNF-α, IL-6 and IL-1β) and restored BDNF levels and the activity of the antioxidant enzymes CAT and GPx in the brain in an HFD-induced anxiety-like behavior model." (PMID 40076566, 2025). "The aim of the current investigation was to evaluate the impact of taVNS intervention applied at three discrete frequencies on locomotor activity, memory, anxiety‐like behaviour and hippocampal gene expression of GFAP, Iba1 and BDNF in animals subjected to morphine." (PMID 40183201, 2025). "In our study, hippocampal BDNF/TrkB expression was significantly down-regulated in the CRS-exposed mice, and pharmacological modulation of this pathway influenced synaptic transmission and anxiety-like behaviors." (PMID 40777598, 2025). "Furthermore, another study showed that inhibition of activated astrocytes after inflammation was able to ameliorate anxiety and depressive-like behaviors induced by lipopolysaccharide in addition to decreasing GFAP and increasing BDNF levels in the brain." (PMID 40015967, 2025). "BDNF Val68Met genotype was shown not to influence anxiety-like behaviors, which is consistent with the current animal literature." (PMID 40045366, 2025). "In contrast, chronic stress protocols extended from 7 days to up to 11 weeks and consistently produced enduring anxiety-like behaviors, social impairments, and molecular alterations such as increased cortisol, dysregulated CRF/BDNF/IL-6 expression, and oxidative stress signatures." (PMID 40427646, 2025). "In this study, peripheral BDNF levels and depressive or anxiety symptoms in CUD were not correlated." (PMID 40943216, 2025). "In contrast to the dynamic interactions observed with cognition and anxiety, our analysis revealed that intrinsic factors, such as age and body composition, acted as stable, non-interactive predictors of BDNF." (PMID 41164095, 2025). "Therefore, our results demonstrated that linalool rescued the BDNF and NGF expression in MPP+-induced neurotoxicity in SH-SY5Y cells and improved depressive- and anxiety-like behaviors in MPTP-induced PD." (PMID 38473763, 2024). "Notably, miR-10a-5p has been identified as a potential biomarker for acute psychological stress and anxiety by downregulating CREB and BDNF levels." (PMID 38410679, 2024).